NLRP3 (NLR family pyrin domain containing 3)
Diseases named in the same sentence as NLRP3 in open-access papers (continued):
Sharing a sentence is not in itself a finding about the gene and the disease.
tumor (continued). "In this study, we found that EEBR promoted nuclear translocation and expression of NF‐κB and activated NLRP3 in A549 and tumour tissues, while BAY treatment reduced the proportion of PI‐positive cells as well as the release of LDH to reverse the EEBR‐induced pyroptosis." (PMID 38214430, 2024). "A variety of tumours show dysregulated expression of the NLRP3 inflammasome, its expression and regulatory mechanism in CRC remain unclear." (PMID 38804602, 2024). "Additionally, we verified that the ROS scavenger MT inhibited NLRP3 inflammasome activation and alleviated the gastric injury index in PHT models, and MT also repressed GC proliferation and attenuated NLRP3 activation in SGC7901 mouse tumour models." (PMID 38616702, 2024). "Moreover, in a CRC mice model, miR-22 retards tumor growth and reduces the expression of Ki-67 in tumor tissue by targeting NLRP3." (PMID 39684769, 2024). "However, increased NLRP3 levels in cancer cells with high NLRP3 activation capacity can increase tumor aggression." (PMID 38543085, 2024). "Although experimental evidence seems to overwhelmingly support the upregulation of the NLRP3 in OC and its association with poorer outcomes, there is also some evidence that NLRP3 expression may have anti-tumour properties." (PMID 39516433, 2024). "Overall, identifying a dysregulated NLRP3 inflammasome signature in premalignant hematological entities could serve both as a biomarker of progression to neoplasia, as well as a possible target to hinder the malignant transformation." (PMID 38397043, 2024). "Changes in cytokine`s levels were statistically increased after the PTX treatment of breast cells (p < 0.0001), suggesting the influence of this anti-tumor drug to interfere with NLRP3 inflammasome activation and pro-inflammatory mediators secretion in TNBC MDA-MB-231 cells." (PMID 39433537, 2024). "NLRP3-mediated immune response and pyroptosis could be helpful or harmful in the progression of cancer, and also depend on the nature of the tumor microenvironment." (PMID 39769450, 2024). "In addition, other studies have found that cellular pyrophosphorylation also in turn promotes NLRP3 inflammatory vesicle activation, thereby promoting tumor cell proliferation and metastasis." (PMID 38734702, 2024). "Additionally, SCFAs like butyrate exert anticolitis effects by activating the NLRP3 inflammasome, while diets high in cholesterol and saturated fats promote NLRP3 activation, exacerbating inflammation and tumor burden." (PMID 39568773, 2024). "Indeed, chronic inflammation activates the NLRP3 inflammasome, which triggers an immunosuppressive response, tumour progression, and metastasis formation." (PMID 39595195, 2024). "Of note, a meta-analysis of VS microarray data showed a correlation between NLRP3 inflammasome and hearing loss in VS irrespective of tumour size." (PMID 38480935, 2024). "In addition, the released ATP by dying tumor cells fosters the formation of caspase-1-dependent NLRP3 inflammasome in DCs and promotes the secretion of IL-1β, further stimulating antitumor immune responses." (PMID 39916954, 2024). "In a subcutaneous tumor model in mice, melatonin has also been observed to elicit marked inhibitory effects on tumor angiogenesis, lymphangiogenesis, and tumor growth through modulation of the NLRP3 axis." (PMID 39230586, 2024). "Therefore, inhibiting NLRP3 was suggested to suppress tumor aggression by reducing the release of inflammatory cytokines." (PMID 38543085, 2024). "A few studies have suggested that blocking the NLRP3 inflammasome/IL-1β pathway may be a potential strategy for treating HNSCC by ameliorating the tumor microenvironment." (PMID 38904007, 2024). "Mice with NLRP3 and caspase-1 deficiency subjected to AOM/DSS showed a dramatically increased tumor burden in the colon due to reduced IL-18 levels that altered the production and activation of the tumor suppressors IFN-γ and signal transducer and activator of transcription 1 (STAT1)." (PMID 39684769, 2024).
tumor (continued). "Expression of NLRP3 is upregulated in bladder cancer, especially at the early tumor stages." (PMID 36932407, 2023). "In primary colorectal tumors, NLRP3 is overexpressed in TAMs along the tumor boundaries." (PMID 36932407, 2023). "Bromonitrozidine (RRx-001) is a minimally toxic, NLRP3 inhibitor that has been observed, in experimental systems, to also downregulate CD47, repolarize tumor associated macrophages (TAMs) and normalize aberrant tumor perfusion." (PMID 36960054, 2023). "Similarly, Nlrp3−/− mice and Caspase-1−/− mice show less and later tumor incidence when challenged with the carcinogen, 4-nitroquinoline 1-oxide (4-NQO)." (PMID 36932407, 2023). "Nlrp3-/- mice developed atypical hyperplasia and tumor formation due to elevated inflammatory responses and disruption of the intestinal epithelial barrier in response to CRC induction by (AOM)/dextransodium sulfate (DSS) and similar results were observed in ASC and caspase-1 deficient mice." (PMID 37081882, 2023). "NLRP3 may influence tumor immunity mainly by mediating tumor-infiltrating lymphocytes and macrophages." (PMID 36891150, 2023). "Collectively, these data suggest that HDM could accelerate lung tumor progression by activating the NLRP3/IL-1β signaling pathway and by creating a pro-tumor lung microenvironment rich in IL-1β+-macrophages, MDSCs, and PD-1+-myeloid cells." (PMID 36670473, 2023). "However, MCC950 significantly reversed the tumor-induced upregulation of Nlrp3 and Il1b gene expression." (PMID 37749707, 2023). "The spatial and temporal activation and expression of AIM2 and NLRP3 in varying tumor types may explain the conflicting reports but more studies are needed to fully understand the importance of the inflammasomes and its components in cancer." (PMID 37449203, 2023). "Alpinumisoflavone, an anticancer drug for the treatment of HCC, could effectively induce cancer cell pyroptosis through NLRP3 inflammasome‐dependent pathway to increase the expression of pyroptosis‐related genes for enhanced tumor inhibition." (PMID 37125240, 2023). "In the tumor tissue, DEX treatment significantly reduced the expression of CTP1A and TXNIP, which are involved in reactive oxygen species (ROS)-related regulatory mechanisms associated with NLRP3 inflammasome activation." (PMID 37528154, 2023). "Hence, the presence of the NLRP3 inflammasome is also necessary in the anti-tumor adaptive immune response." (PMID 37497237, 2023). "MDSCs exhibit an increased activation of NLRP3 during tumor development." (PMID 36911674, 2023). "Moreover, IL-1, and NLRP3 were also upregulated, indicating development of an inflammasome signature in the tumor." (PMID 37771579, 2023). "Interestingly, CD146 was involved in the NLRP3 inflammasome-mediated activation of macrophages in the tumor microenvironment, partially by inhibiting transmembrane protein 176B (TMEM176B), an immunoregulatory cation channel." (PMID 37308559, 2023). "Furthermore, we identified several tumour-associated macrophages, including C1QC+ macrophages, ISG-15+ macrophages, NLRP3+ macrophages and CCL20+ macrophages." (PMID 37735150, 2023). "It is still elusive whether this paclitaxel-mediated NLRP3 activation is able to facilitate anti-tumor immunity." (PMID 36932407, 2023). "The NLRP3 inflammasome can also impair the efficacy of anti-tumor vaccines." (PMID 37497237, 2023). "Our studies show that NLRP3 inhibition reduces the PDAC-associated immunosuppression without affecting tumor cells proliferation." (PMID 37772994, 2023). "Although the use of animal models could provide data on the interaction between tumor and immune cells, the primary objective of this work was to determine the endogenous baseline NLRP3 inflammasome levels and IL‐1β secretion of CM and UM." (PMID 36707938, 2023).
tumor (continued). "For instance, this crucial NLRP3 inflammasome effector molecule could also inhibit the proliferation of cytotoxic cells (e.g. natural killer cells) to promote tumor growth and metastasis formation by inducing the expression of programmed death 1 (PD1)." (PMID 37205092, 2023). "Another study found that human stanniocalcin-1 could reduce the volume of HCC tumor tissue by upregulating NLRP3 signaling pathway." (PMID 37020871, 2023). "Activated CD8+ T cells may further promote the activation of NLRP3 inflammasomes of antigen-presenting cells through perforin-dependent mechanisms and achieve anti-tumor effects through a positive feedback mechanism." (PMID 37497237, 2023). "NLRP3 has been reported to promote the invasion and metastasis of tumor cells in some cases." (PMID 36932407, 2023). "Moreover, the 12Gy + NLRP3 agonist achieved better primary tumor control than the 5Gy treatment regimen in 344SQ-P model." (PMID 37289257, 2023). "Collectively, we show that tumor‐released lactate could trigger IL‐1β secretion from Mφ by activating the NLRP3 inflammasome." (PMID 37009412, 2023). "Next, we determined whether the reduction in tumor growth following NLRP3 inhibition was T-cell dependent." (PMID 37772994, 2023). "The inclusion of NLRP3-driven inflammation adds additional impetus to such treatment because it has been manifested that NLRP3 activation in various tissues can activate NK cell responses, which may contribute to tumor clearance." (PMID 37715239, 2023). "Similarly, NLRP3 from a subgroup of CD11b+ Gr-1int myeloid cells has been shown to foster tumor metastasis of B16-F10." (PMID 36932407, 2023). "Furthermore, NLRP3 depletion in HCC model was reported to increase the cytotoxic ability of NK cells on tumor cells." (PMID 37891577, 2023). "It remains to be investigated how NLRP3 deficiency, and IL-18R and IL-1R signaling affect the earlier phases of T-cell motility, such as the T-cell scanning of APC in lymph nodes, CTL egress, or entry from the blood stream into tumor tissue." (PMID 36766797, 2023). "However, we only observed minimal overlap between NLRP3 and the oxidative tumor‐DNA in the Arf1‐ablation‐stimulated DCs." (PMID 37786300, 2023). "Since NLRP3 could also be activated by oxidative DNA, we further examined the tumor‐derived oxidative DNA by using a specific antibody in the Arf1‐ablation‐stimulated DCs." (PMID 37786300, 2023). "Therefore, predicting the effects of chemotherapy drugs on tumor growth requires prior testing of the NLRP3 expression status." (PMID 36902278, 2023). "In conclusion, we speculated that NLRP3 may cooperate with AL365361.1 to regulate the tumor microenvironment, ICIs response, and play a tumor suppressor role in HCC." (PMID 36672493, 2023). "Hence, we assessed the effect of XRT escalation on NLRP3 expression at the mRNA level in macrophages and tumor cells separately in vitro." (PMID 37289257, 2023). "To find the possible correlation between the expression of these five NLRP3 inflammasome pathway-related proteins in tumor tissues and patients’ clinicopathological characteristics, we separated all 5 molecular into low and high expression groups according to the IHC score." (PMID 38031068, 2023). "However, the release of various DAMPs, including ATP, HMGB1 and IL-1α, from dead tumor cells activates the NLRP3 inflammasome in DCs, which can lead to resistance to chemotherapy and promote tumor growth." (PMID 37497237, 2023). "In addition, NLRP3 inflammasome activation by nigericin induced pyroptotic cell death on BRAF V600 inhibitor‐resistant CM tumor cells." (PMID 36707938, 2023). "It is worth noting that in this study, the dual role of Nrf2 and the NLRP3 inflammasome in tumors was observed; that is, they could prevent tumor development, but once the tumor develops, they have a promoting effect." (PMID 37833958, 2023). "Therefore, it is essential to neutralize the effect of NFkB so as to overcome the pro-tumor activity of the NLRP3 inflammasome." (PMID 37893079, 2023).
tumor (continued). "The NLRP3 inflammasome is considered to be a double-edged sword in cancer as it may either promote or suppress tumor growth." (PMID 36763290, 2023). "The NLRP3 inflammasome facilitates the invasion of myeloid cells into TMEs like myeloid‐derived suppressor cell (MDSC) and tumor‐associated macrophage (TAM), which benefits tumor progression." (PMID 37752941, 2023). "In this study, we identified that chronic exposure to HDM activates the NLRP3 inflammasome in macrophages, increases the production of IL-1β in the lungs, induces a pro-tumor lung microenvironment, and accelerates LC development and progression in two different mouse models." (PMID 36670473, 2023). "In BC, the clinical analysis showed that NLRP3 and PYCARD expressions were strongly associated with more aggressive clinicopathological factors such as tumor size and proliferative index Ki67 and contributed to BC progression, especially in luminal BC patients." (PMID 37762557, 2023). "VTPA was able to rupture the lysosome of tumor cells, and significantly increased the expression of trypsin B, NLRP3, caspase‐3, GSDMD‐N, and other inflammatory bodies and pyroptosis biomarkers, confirming the ability of VTPA to induce pyroptosis of tumor cells." (PMID 37933288, 2023). "In different situations, the downstream mechanisms of the NLRP3 activation might promote or inhibit the malignant behaviors of tumors including tumor growth, metastasis, and drug resistance." (PMID 36932407, 2023). "Similarly, Berberine can affect tumor outgrowth and spontaneous metastasis in TNBC through a mechanism associated with inhibition the NLRP3 inflammasome pathway." (PMID 37259036, 2023). "The result revealed the inhibition of the proliferation ability of both H446 and A549 by MCC950, indicating that the suppression of NLRP3 may inhibit tumor growth and alleviate the progression of RILI." (PMID 36694200, 2023). "When inhibiting the expression of LncRNA-XIST oncogene, it could activate NLRP3 inflammatory bodies, increase the expression of caspase-1 and IL-1β, and then induce pyroptosis of tumor cells, ultimately inhibiting the occurrence and development of NSCLC." (PMID 37194012, 2023). "Therapeutical strategies targeting the NLRP3 inflammasome in OC involve the use of Oridonin, which, through the suppression of the mTOR pathway, arrests OC spread, and Tranilast, which enhances the sensitivity of tumor cells to Cisplatin." (PMID 37891577, 2023). "The Mon Fn1 cell population is characterized by inflammatory features, including increased expression of the chemokine receptors Ccr2 and Ccr1 facilitating cell recruitment, immune suppression and tumor-promoting factors such as galectins (Lgals3/9), and the NLRP3 inflammasome inhibitor Tmem176b." (PMID 37756565, 2023). "The recently identified tumor-intrinsic PD-L1/NLRP3 inflammasome signaling pathway suggests that NLRP3 inflammasome inhibition could be a therapeutic target when combined with PD-1/PD-L1 immunotherapy." (PMID 37242422, 2023). "For instance, some studies suggest that the anaplastic lymphoma kinase (ALK) inflammasome component is required for NLRP3 activation in macrophages and that NLRP3 inflammasome activation might play a pro-tumor role through the IL-18 effector cytokine." (PMID 37205092, 2023). "Abnormal activation of the NLRP3 inflammasome has been associated with various chronic inflammation and is known to be overexpressed in OSCC cells and tissues, allowing it to be associated with tumor stage and lymph node metastasis." (PMID 37081882, 2023). "Finally, recent works have demonstrated that blocking NLRP3 pathway in PC-3 cells and PCa-derived xenografts have a significant impact on tumor progression by disrupting cell proliferation, migration, and/or inducing apoptosis." (PMID 37819510, 2023). "Other studies have shown that NLRP3 played an important role in promoting tumor metastasis." (PMID 37833958, 2023).
tumor (continued). "In close correlation with the development of inflammatory reactions and TNBC is the activation of the NLRP3 inflammasome complex, with IL-1β and IL-18 being the two major cytokines activated by NLRP3 inflammasome, which promote tumor cell proliferation and invasion." (PMID 36834660, 2023). "By blocking NLRP3 signaling, Avastin effectively inhibits tumor growth." (PMID 37497237, 2023). "Notably, tumor-bearing mice treated with anti-CSF-1R showed a reduction in the colocalization of NLRP3 and ASC that resulted in a significant decrease in the formation of ASC specks." (PMID 37772994, 2023). "Also, our data further advance our understanding of the mechanisms of NLRP3 activation in hormone-dependent BC tumor cells." (PMID 36902278, 2023). "Pyroptosis is suppressed in MM tumor cells judged from the low expression of NLRP3 and caspase-1." (PMID 38016064, 2023). "NLRP3 inflammasomes are also essential for tumor-specific adaptive immunity." (PMID 36902299, 2023). "The addition of α-PD1 did significantly improve performance of the NLRP3 agonist in combination with 5Gy XRT in both tumor models (P = 0.017 and P < 0.0001, respectively); however, α-PD1 did not boost the strength of 12Gy XRT + NLRP3 combination in regards to primary tumors (all P > 0.05)." (PMID 37289257, 2023). "NLRP3 activation might have differential effects not only on different cell types (such as tumor, myeloid, and T cells), but also on the various stages of the life cycle at which a T cell, for example, might be." (PMID 36766797, 2023). "Finally, changes in NLRP3 inflammasome activation influence malignant transformation, tumor growth, and therapeutic response through influencing a complicated network of cancer cell activities." (PMID 37715239, 2023). "Whether their anti-tumor effects are underpinned by NLRP3 inhibition remains to be further evaluated." (PMID 36932407, 2023). "In agreement with a previous study, we found that budesonide inhibits NLRP3 and decreases IL-1β production by macrophages, which could explain, at least in part, its anti-tumor effect." (PMID 36670473, 2023). "Indeed, there are several conflicting studies in various types of cancer showing that NLRP3 can either favor tumor growth or act as a tumor suppressor." (PMID 37298187, 2023). "Moreover, tumor growth was observed to be accelerated in NLRP3 knockout mice, concomitant with decreased IL-18 levels in the tissue." (PMID 37497237, 2023). "Knockdown of MEG3 could reverse the inhibition of cisplatin on tumor growth and metastasis thorough NLRP3/caspase‐1/GSDMD pathway‐mediated pyroptosis." (PMID 36237132, 2023). "The recently identified tumor-intrinsic PD-L1/NLRP3 inflammasome signaling pathway suggests that NLRP3 inflammasome inhibition could be a therapeutic target in combination with PD-1/PD-L1 immunotherapy." (PMID 37242422, 2023). "Furthermore, the NLRP3 inflammasome is well known to contribute to the formation of a tumor immunosuppressive microenvironment." (PMID 37524704, 2023). "The tumor suppressor miR-22 is another microRNA involved in NLRP3 regulation." (PMID 37300757, 2023). "Moreover, the over‐expressed cGAS and cytosolic sensor NLRP3 colocalized with the tumor‐derived DNA and exogenous oxLDL in DCs, respectively." (PMID 37786300, 2023). "Recently, a study to illustrate the mechanism of Salmonella immunotherapy suggested the necessity of NLRP3 engagement as well as the recruitment of macrophages to tumor microenvironment, supporting the position participation of NLRP3 inflammasome in antitumor activity." (PMID 37817895, 2023). "In a mouse CRC-liver metastasis model, the NLRP3 inflammasome increases IL-18 secretion, promotes maturation of hepatic NK cells, increases FasL expression, and Fas/FasL interaction can exert cytotoxicity on tumor cells." (PMID 37081882, 2023).